RN7SL432P (RNA, 7SL, cytoplasmic 432, pseudogene)
Gene: Miscellaneous RNA gene on chromosome 1 (114,697,627 to 114,697,924, reverse strand). Ensembl gene ENSG00000242769.
Homologues: Orthologues: chimpanzee Metazoa_SRP (98% identical), macaque Metazoa_SRP (90% identical). Paralogues in human: RN7SL2 (82% identical), RN7SL1 (81% identical), RN7SL3 (81% identical), RN7SL732P (80% identical), RN7SL126P (78% identical), RN7SL664P (78% identical), RN7SL49P (78% identical), RN7SL113P (78% identical), RN7SL122P (78% identical), RN7SL147P (78% identical), RN7SL712P (78% identical), RN7SL778P (78% identical), and 701 more.